ETV1 (ETS variant transcription factor 1)
Diseases named in the same sentence as ETV1 in open-access papers (continued):
Sharing a sentence is not in itself a finding about the gene and the disease.
triple-negative breast carcinoma (6 papers, 2015 to 2020). An invasive breast carcinoma which is negative for expression of estrogen receptor (ER), progesterone receptor (PR), and human epidermal growth factor receptor 2 (HER2). "A study of the clinical effect of Etv1 demonstrated that the ETV1-positive group was associated with a markedly poor overall survival in triple-negative breast cancer." (PMID 31109321, 2019). "However, the co-existing status of ETV1 and COP1 in triple-negative breast cancer (TNBC) and their predictive role in determining the patient’s outcome are uncertain." (PMID 25884720, 2015).
colon cancer (5 papers, 2020 to 2024). "To further explore the relationship between ETV1 and various immune infiltrating cells (IICs), we evaluated the relationship concerning ETV1 and immune marker sets of diverse immune cells of colon cancer in TIMER and GEPIA." (PMID 35860243, 2022). "In conclusion, our data have uncovered a ETV1/JMJD1A/JMJD2A→BHLHE40 axis in colon cancer cells." (PMID 36890812, 2023). "PEA3 subfamily of ETS transcription factors (ETV1, ETV4, and ETV5) are upregulated in multiple cancers including colon cancers." (PMID 33658938, 2020).
hepatocellular carcinoma (5 papers, 2021 to 2025). A malignant tumor that arises from hepatocytes. "Additionally, HCC patients with ETV1/PTK2 or ETV1/c-MET co-positive hepatocellular carcinoma in two different cohorts had a worse prognosis." (PMID 36407100, 2022).
lung adenocarcinoma (5 papers, 2021 to 2023). A carcinoma that arises from the lung and is characterized by the presence of malignant glandular epithelial cells. "miR-1224-3p has been reported to target ETV1 in lung adenocarcinoma cells." (PMID 33986801, 2021). "(b) Heat map of the PEA3 family ETS transcription factors (ETV1, ETV4, and ETV5) and neuroendocrine transcription factors (ASCL1, NEUROD1, INSM1, and POU3F2 [BRN2]) in small cell lung cancer and lung adenocarcinoma cell lines." (PMID 34121659, 2021).
metastatic tumors (5 papers, 2010 to 2023). "In fact, patients with high ETV1 frequently had a metastatic disease, and are associated with a poor prognosis; furthermore, patients with high ETV1 expression and loss of PTEN displayed a much poorer disease-free survival." (PMID 31366128, 2019).
prostate intraepithelial neoplasia (4 papers, 2015 to 2022). A neoplastic proliferation of the epithelial cells that line the acini and the ducts of the prostate gland. "When YAP1 activation is induced in vivo by ETV1, it causes prostatic intraepithelial neoplasia (PIN) lesion formation, which when combined with a single copy loss of PTEN, progresses to malignant carcinoma." (PMID 35954292, 2022). "Also, COP1 deficiency in mouse prostate elevated ETV1 and increased cell proliferation, hyperplasia, and early prostate intraepithelial neoplasia." (PMID 25884720, 2015). "Accordingly, transgenic mice that prostate-specifically overexpress ETV1 develop prostatic intraepithelial neoplasia." (PMID 31160676, 2019). "In addition, COP1 deficiency increased cell proliferation, hyperplasia, and early prostate intraepithelial neoplasia by elevating ETV1 expression in mouse prostate." (PMID 25884720, 2015).
liver cancer (3 papers, 2022 to 2025). An epithelial or non-epithelial malignant neoplasm that arises from the liver. "Our mechanistic investigations identified LAPTM4B as a crucial gene regulated by ETV1 (a transcription factor), especially in liver cancer stem cells (LCSCs)." (PMID 38388484, 2024). "A recent publication reported that ETV1 might contribute to the aggressiveness of liver cancer stem cells by regulating LAPTM4B, a factor involved in tumour cell proliferation and metastasis." (PMID 40275610, 2025). "Western-blotting was conducted for ETV1 and LAPTM4B expression in liver cancer cells." (PMID 38388484, 2024).
neuroblastoma (3 papers, 2017 to 2020). Neuroblastoma (NB) is the most common solid, extracranial childhood tumor. "Here we show that YK-4-279 suppressed growth and triggered apoptosis in nine neuroblastoma cell lines, while BRD32048, another ETV1 inhibitor, was ineffective." (PMID 28602975, 2017).
type 2 diabetes (3 papers, 2022 to 2025). "Furthermore, ETV1 was enriched in beta cells from donors with type 2 diabetes, increased ETV1 expression was associated with reduced exocytosis, and knockdown of ETV1 rescued exocytosis specifically in these beta cells." (PMID 35482056, 2022). "In addition, we discovered seven other potential key transcriptional regulators of gene expression networks in type 2 diabetes: Etv1, Irx1 and Foxp1 (alpha cells); Ehf, Hhex and Tcf4 (delta cells); and Zfhx3 (macrophages)." (PMID 39508880, 2025).
atrial fibrillation (2 papers, 2020 to 2024). A disorder characterized by an electrocardiographic finding of a supraventricular arrhythmia characterized by the replacement of consistent P waves by rapid oscillations or fibrillatory waves that vary in size, shape and timing and are accompanied by an irregular ventricular response. "The E‐twenty‐six variant 1 (ETV1)‐dependent transcriptome plays an important role in atrial electrical and structural remodelling and the occurrence of atrial fibrillation (AF), but the underlying mechanism of ETV1 in AF is unclear." (PMID 39159135, 2024). "The ETS-related transcription factor ETV1 was identified as an atrial-specific element involved in the pathogenesis of atrial fibrillation." (PMID 32193645, 2020).
autism (2 papers, 2020 to 2023). Persistent deficits in social interaction and communication and interaction as well as a markedly restricted repertoire of activity and interest as well as repetitive patterns of behavior. "Among these putative ETV1 targets are CSF2RB, which has been associated with major depression and schizophrenia, and MIS18BP1, a gene implicated in the autism spectrum." (PMID 36449109, 2023).
breast tumor (2 papers, 2010 to 2011). "Although overexpression of PEA3 (E1AF/ETV4), and of the related factors ERM (ETV5) and ER81 (ETV1), have been observed in human and mouse breast tumors, PEA3 factors have also been ascribed a tumor suppressor function." (PMID 20107508, 2010).
diabetes (2 papers, 2017 to 2023). "In another diabetes mellitus model, EA increased the c-Kit, mSCF, and ETV1 expressions in the antrum and corpus, thereby accelerating gastric emptying." (PMID 37351066, 2023). "So far, there have been limited reports about the SCF/Kit-ETV1 signaling in diabetes." (PMID 28203258, 2017). "Nevertheless, at present, no reports about ETV1 have been published in models of diabetes and EA." (PMID 28203258, 2017).
epilepsy (2 papers, 2016 to 2021). A brain disorder characterized by episodes of abnormally increased neuronal discharge resulting in transient episodes of sensory or motor neurological dysfunction, or psychic dysfunction. "It should be noted, however, that the ETS expression profile is also different in epilepsy; ELF1, ELK1, ELK4, ETS1, ETS2, and ETV1 are expressed at higher levels than ELF4, ELK3, and ETV4, and there is also variability in expression among different types of epilepsy." (PMID 33671331, 2021).
esophageal adenocarcinoma (2 papers, 2010 to 2022). A malignant tumor with glandular differentiation arising predominantly from Barrett mucosa in the lower third of the esophagus. "Here, we have studied the expression of the PEA3 subfamily members PEA3/ETV4 and ER81/ETV1 in oesophageal adenocarcinomas and determined their role in oesophageal adenocarcinoma cell function." (PMID 21143918, 2010).
gastric adenocarcinoma (2 papers, 2018 to 2020). "Another possible mechanism that a gastric adenocarcinoma might trigger the proliferation of the ICCs by inducing an elevated ETV1 expression and hereby contribute to the development of a GIST." (PMID 33335133, 2020). "Moreover, both in the ETV1 positive gastric adenocarcinomas and GISTs, we have observed a prevalent cytoplasmic positivity and only a small proportion of the positive cells showed nuclear/cytoplasmic subcellular localization pattern." (PMID 33335133, 2020). "ETV1 oncoprotein was reported to induce the epithelial-to-mesenchymal transition (EMT)-like metastatic progression and increased invasiveness/aggressiveness of gastric adenocarcinomas by upregulation of SNAIL expression, a classical EMT driver gene." (PMID 29642018, 2018).
glioblastoma (2 papers, 2022 to 2023). The most malignant astrocytic tumor (WHO grade IV). "In glioblastoma, SRSF3 promotes the exon 7 inclusion of ETV1 and mutually exclusive of the exon 9 of NDE1 to promote tumorigenesis." (PMID 37558679, 2023).
mesothelioma (2 papers, 2013 to 2015). A usually malignant and aggressive neoplasm of the mesothelium which is often associated with exposure to asbestos. "Most of these SNPs were located in regions reported to harbor aberrant alterations in mesothelioma (SLC7A14, THRB, CEBP350, ADAMTS2, ETV1, PVT1 and MMP14 genes), causing at most a 2–3-fold increase in MPM risk." (PMID 23626673, 2013).
non-small cell lung carcinoma (2 papers, 2017 to 2022). A group of at least three distinct histological types of lung cancer, including non-small cell squamous cell carcinoma, adenocarcinoma, and large cell carcinoma. "ETV1 is a DE TF regulated by miR-582-5p, which was recently proposed as an oncogene in non-small cell lung cancer." (PMID 29207642, 2017).
skin cancer (2 papers, 2013 to 2017). "Our analysis also identified several new UV target genes, including CYP24A1, GJA5, SLAMF7 and ETV1, which were frequently dysregulated in human squamous cell carcinomas, highlighting their potential as new molecular targets for prevention or treatment of UVR-induced skin cancers." (PMID 28211524, 2017).
skin squamous cell carcinoma (2 papers, 2022). A carcinoma arising from the squamous cells of the epidermis. "In skin squamous cell carcinomas, upregulation of ETV1 was sufficient to induce most CAF effectors upregulated by fibroblast growth factor (FGF), which could promote the secretion of multiple chemokines with macrophage-recruiting activity including CXCL1, CXCL10, and CXCL11." (PMID 35860243, 2022). "Moreover, ETV1 is reported to be significantly upregulated by FGF2 treatment and downregulated by TGF-β1, thus generating distinct cancer-associated fibroblasts populations to promote skin squamous cell carcinoma development." (PMID 36109787, 2022).
thyroid cancer (2 papers, 2020 to 2024). "We detect a number of recurrent fusions, such as those involving ANO3, RGS9, FUT5, CHI3L1, OR1D4, and LIPG in breast; IGF2 in colon; ETV1 in prostate; and IGF2BP3 and SIX2 in thyroid cancers." (PMID 32631391, 2020).
Arrhythmia (1 paper, 2022). Any cardiac rhythm other than the normal sinus rhythm. "For example, the ETS transcription factor Ets1 has been shown to mediate angiotensin II-related cardiac fibrosis and cardiac hypertrophy, while increased ETV1 activity has been shown to induce atrial remodeling and arrhythmia." (PMID 35236346, 2022).
astrocytoma (1 paper, 2019). "The loss of CIC protein in patient-derived samples correlated with de-repression the CIC targets, ETV1 and ETV5, in human GBM and in lower-grade astrocytoma." (PMID 30737375, 2019).
atrial flutter (1 paper, 2024). A disorder characterized by an electrocardiographic finding of an organized, regular atrial rhythm with atrial rate of 240-340 beats per minute. "AF and episodes of atrial flutter were labelled as AF, AF was induced by 30 Hz pulse pacing in 12 of 40 (30%) ETV1‐CKO mice, just 1 of 30 (3.33%) in WT mice (p < 0.05)." (PMID 39159135, 2024).
brain tumor (1 paper, 2020). "CIC was found to be expressed in several GBM and primary brain tumor-initiating cell (BTIC) lines despite exhibiting increased expression of CIC target genes downstream of MAPK (ETV1/4/5, DUSP6, SPRY4), compared to NHA cells." (PMID 33115448, 2020).
cardiac interstitial fibrosis (1 paper, 2025). "Masson staining showed that increased expression of ETV1 by AAV9-Etv1 transfection significantly alleviated cardiac interstitial fibrosis compared with AAV9-NC MI mice in the border regions, as evidenced by reduced collagen deposition." (PMID 40894482, 2025).
cardiomyopathies (1 paper, 2025). "Furthermore, human ETV1 variants have been associated with conduction disease, highlighting the potential role of the Nrg1-Etv1 axis in the pathogenesis of LVNC and related cardiomyopathies." (PMID 40558659, 2025).
carpal tunnel syndrome (1 paper, 2026). Entrapment of the median nerve in the wrist that is characterized by numbness, tingling and painful movement. "These included associations with genes involved in neurotransmitter signaling (HTR3A), immune function (HLA-DQB1, BCL11A), extracellular matrix remodeling (COL11A1, ADAMTS17, LOXL4), axon guidance and neural development (DCC, ETV1, NEGR1), and carpal tunnel syndrome (DIRC3)." (PMID 41518141, 2026).
cognitive decline (1 paper, 2020). "Changes in ETV1 expression have likewise been linked with cognitive decline." (PMID 32211019, 2020).
colitis (1 paper, 2025). Inflammation of the colon. "Pharmacological inhibition of ETV1 ameliorates colitis in recombination activating gene 1-deficient mice and suppresses human IBD T cell responses ex vivo." (PMID 41347630, 2025). "Moreover, Etv1 deficiency attenuates CD45RBhighCD4+ T cell-induced colitis, characterized by a reduction in pathogenic CD4+ T cells in the intestinal mucosa." (PMID 41347630, 2025). "Etv1 deficiency impairs CD4+ T cell activation, proliferation, and T helper 17 (Th17) cell differentiation, thereby ameliorating TNBS-induced colitis." (PMID 41347630, 2025).
colorectal adenocarcinoma (1 paper, 2023). The most common type of colorectal carcinoma. "In further support of this notion, BHLHE40 mRNA levels are positively correlated with ETV1, JMJD1A and JMJD2A in the 592 colorectal adenocarcinomas represented in The Cancer Genome Atlas (TCGA)." (PMID 36890812, 2023).
colorectal tumors (1 paper, 2023). "Since ETV1, JMJD1A and JMJD2A are implicated in many different types of malignancies, BHLHE40 upregulation by these three proteins is likely not limited to colorectal tumors." (PMID 36890812, 2023). "Both ETV1 and JMJD1A are reportedly overexpressed in colorectal tumors, providing one plausible explanation for BHLHE40 upregulation in this cancer." (PMID 36890812, 2023).
conduction disorders (1 paper, 2018). "Moreover, our data suggest that the ETV1-dependent rapid conduction GRN can be modulated for the management of selected human conduction disorders." (PMID 29967479, 2018).
Ewing's sarcoma family tumors (1 paper, 2008). "The EWS-FLI-1 fusion protein is associated with 85–90% of Ewing's sarcoma family tumors (ESFT), the remaining 10–15% of cases expressing chimeric genes encoding EWS or FUS fused to one of several ets transcription factor family members, including ERG-1, FEV, ETV1 and ETV6." (PMID 18648544, 2008).
germ cell tumours (1 paper, 2023). "Six of these genes, including Etv1, Etv4, Ret, Tdgf1, Pdk1 and Calcoco, have been associated with germ cell tumours, stem cells, cell self-renewal, cancer, cell proliferation and cell survival." (PMID 38053127, 2023). "Further examination of the genes that were lower than expected revealed six FGFRi-MEKi DEGs associated with stem cell differentiation, cell self-renewal, cancer, cell proliferation and survival and germ cell tumours, including Etv1 and Etv4, Pdk1, Ret, Tdgf1 and Calcoco2." (PMID 38053127, 2023).
Hypertension (1 paper, 2024). The presence of chronic increased pressure in the systemic arterial system. "In summary, caffeine induces higher expression of the ETV1 and GABP transcription factors, which then bind preferentially to the reference allele at rs4938344; this results in lower expression of AP000892.6 and increased risk for CAD and hypertension." (PMID 38334359, 2024).
ischemic heart disease (1 paper, 2025). "Despite these shortcomings, our study suggested a potential role of ETV1 in therapeutic angiogenesis for ischemic heart disease." (PMID 40894482, 2025).
leiomyoma (1 paper, 2020). A well-circumscribed benign smooth muscle neoplasm characterized by the presence of spindle cells with cigar-shaped nuclei, interlacing fascicles, and a whorled pattern. "On the other hand, non-GISTs (adenocarcinoma, schwannoma and leiomyoma) exhibited significantly lower ETV1 mRNA expression than GISTs." (PMID 32901065, 2020).
lymph node metastasis (1 paper, 2005). "Expression of ETV1 was detected in all tissue types except lymph node metastasis." (PMID 16042785, 2005).
metastasis (1 paper, 2005). The spread or migration of cancer cells from one part of the body (where they first appeared) to another. "Finally, ETS translocation variant 1 (ETV1), a member of the ETS transcription factor family, was expressed in normal and primary tumor, not in lymph node metastasis (although it is a LNCaP unique gene), and potentially elevated in bone metastasis." (PMID 16042785, 2005).
metastatic melanoma (1 paper, 2015). A melanoma that has spread from its primary site to another anatomic site. "Another work has identified copy gains of ETV1 gene present in 13% of primary and 18% of metastatic melanomas, which correlated with enhanced proliferation." (PMID 26158900, 2015).
metastatic prostate carcinoma (1 paper, 2024). A carcinoma that arises from the prostate gland and has spread to other anatomic sites. "Of note, an ETV1 mutation at G74 has been identified previously in a patient with metastatic prostate cancer." (PMID 38667288, 2024).
mucinous tumors (1 paper, 2021). "Finally, RNA expression of differentiation marker FOXA2 and CSC marker ETV1 was higher in PDS derived from mucinous tumors compared to PDS derived from epithelial tumors." (PMID 33356003, 2021).
Niemann-Pick disease (1 paper, 2019). A group of inherited, severe metabolic disorders in which sphingomyelin accumulates in lysosomes in cells. "Finally, we sought to test if induction of KLF2 and ETV1 in ASM-deficient cells contributes to Niemann Pick disease pathology or if it is a protective mechanism." (PMID 30775969, 2019).
Obesity (1 paper, 2021). Accumulation of substantial excess body fat. "High-fat diet (HFD)-induced obesity in mice reduces gene expression of Etv1, Isl1, Mlxipl, Nkx2.2 and Rfx6 whereas Cck, Gip and Pyy, Gcg gene expression is not impacted." (PMID 33037328, 2021).
oligodendroglioma (1 paper, 2019). A well-differentiated (WHO grade II), diffusely infiltrating neuroglial tumor, typically located in the cerebral hemispheres. "RNAseq data from TCGA identified 221 differentially expressed genes in CIC mutant versus wild-type oligodendrogliomas (fold cutoff of 1.5, p-value < 0.05 and FDR < 10%) amongst which the known CIC targets ETV1, ETV4, and ETV5 were significantly up-regulated in CIC-mutant cases." (PMID 30737375, 2019).
ovarian carcinoma (1 paper, 2023). A malignant neoplasm originating from the surface ovarian epithelium. "Similarly, ETV1 is activated by HER2/Neu in high-risk female tumors (breast, endometrial, and ovarian cancers), mediating the malignant tumor phenotype." (PMID 37197420, 2023).
sphingomyelinase deficiency (1 paper, 2019). "Our data in cellular and mouse models of Niemann-Pick-C disease and acid sphingomyelinase deficiency shows, however, that in addition to defective autophagy there is a signaling mechanism based on the induction of two transcription factors, KLF2 and ETV1, which repress mitochondrial biogenesis." (PMID 30775969, 2019).